BMI1 (BMI1 proto-oncogene, polycomb ring finger)
Diseases named in the same sentence as BMI1 in open-access papers (continued):
Sharing a sentence is not in itself a finding about the gene and the disease.
glioma (continued). "Collectively, DANCR knockdown inhibited cell proliferation, migration and invasion of glioma through regulating miR-135a-5p/BMI1, providing viable therapeutic avenues for treatment of glioma." (PMID 32099526, 2020). "The expression of GLI1, GLI2, GLI3 and their target genes FOXM1 and BMI1 was analyzed by RT-qPCR for 20 glioma cell lines and a normal adult brain tissue." (PMID 30730955, 2019). "In the subsets of gliomas, the BMI1 gene is aberrant at the chromosomal level, positively contributing to the pathogenesis of brain tumors." (PMID 30658672, 2019). "Our work highlights the role of DHHC proteins in the plasticity of GBM subsets and reveals that BMI1 represents a potential therapeutic target for human gliomas." (PMID 30658672, 2019). "Based on our previous findings that Bcl11b-KD reduced the expression of stemness-related genes (Sox2 and Bmi1) in glioma cells, we also examined the expression of stemness-related genes in the scramble and Bcl11b-KD cultures." (PMID 29416501, 2018). "By targeting BMI1, miR-218 affects the migration, invasion, and proliferation of glioma cells and blocks self-renewal ability." (PMID 29401683, 2018). "Mechanistically, miR-128 has been found to reduce glioma cell proliferation and promote stem cell self-renewal, by the regulation of the BMI-1 oncogene." (PMID 29568354, 2018). "The reported effects of miR-128 on glioma cells include Bmi-1 downregulation resulting in decreased glioma stem cell self-renewal." (PMID 29445170, 2018). "In accordance with our expectation, knockdown of Bmi1 expression in glioma cells dramatically decreased their expression of both HK2 mRNA and protein level." (PMID 29220380, 2017). "To further assess the contribution of miR-218 and Bmi1 on glioma development, we examined the expression levels of pAKT and HIF-1α, which belong to the PI3K pathway." (PMID 29220380, 2017). "Bmi1, another glioma stem cell marker, belongs to the Polycomb-group gene family, which can promote self-renewal and cellular proliferation." (PMID 29246031, 2017). "pAKT and HIF-1α are involved in the PI3K pathway, and we provided evidence that these proteins were upregulated in both overexpression of miR-218 and knockdown of Bmi1 glioma cell lines." (PMID 29220380, 2017). "Taken together, our findings confirmed the tumorigenic activity of HK2 in glioma, and the involvement of the miR218/Bmi1 pathway in the regulation of its expression." (PMID 29220380, 2017). "For example, NRF2 knockdown decreases self-renewal capacity of glioma stem cells by significant reduction of the expression of stem-like cell markers as Bmi1, Sox2 and Cyclin E." (PMID 28671577, 2017). "Our previously established fact that Bmi1 is a direct functional target of miR-218 in glioma condition validates the miR-218 induced HK2 suppression." (PMID 29220380, 2017). "Both the inhibition of NF-κB activity and knockdown of BMI1 result in decreased angiogenesis in orthotopically transplanted human gliomas." (PMID 28598356, 2017). "As an tumor suppressor in glioma, miR-128 inhibits glioma cells proliferation and self-renewal via targeting BMI1, E2F3a and mitogenic kinases." (PMID 28146425, 2017). "During the process of glioma angiogenesis, NF-κB is induced downstream of the transcription factor, BMI1 proto-oncogene, polycomb ring finger (BMI1), whose activity is required for expression of both NF-κB and VEGF." (PMID 28598356, 2017). "Despite these limitations, this study supports/demonstrates the tumorigenic activity of HK2 in glioma condition, while also establishes a novel miR-218/Bmi1/HK2 axis in regulating the same." (PMID 29220380, 2017). "The HK2 expression in (a) lentivirus-infected, miR-218 overexpressing and (b) shRNA mediated Bmi1 silenced U87 and U251 glioma cell lines were quantified." (PMID 29220380, 2017).
glioma (continued). "In this study we combined the tumor cell specific markers in a double immunofluorescence protocol with the following panel of stem cell markers: CD133, Nestin, Musashi-1, Sox-2 and Bmi-1, to characterize the phenotype of migrating glioma cells." (PMID 27171431, 2016). "Our results confirmed the published data that miR-128 inhibits glioma proliferation and self-renewal via targeting Bmi-1 and revealed a new mechanism by which miR128-1 is deregulated in glioma." (PMID 27705931, 2016). "The expression of Bmi-1 was significantly reduced in the periphery of grade II tumors and all gliomas together." (PMID 27171431, 2016). "Consistent with the observations in prostate cancer, our study found that miR128-1 negatively regulated BMI1 expression in glioma cells through its predicted miR128-1 binding site." (PMID 27705931, 2016). "BMI1 also plays a role in stem cell renewal and serves as a neural stem cell and glioma maintenance factor." (PMID 27705931, 2016). "For example, overexpression of miR-124 reduced neurosphere formation, CD133+ cell subpopulations, and stem cell markers such as BMI1, Nanog, and nestin in glioma cells." (PMID 27824145, 2016). "The oncogenic BMI1 protein sustains glioma stem cell renewal, promotes cell growth and renders protection from apoptosis." (PMID 25831237, 2015). "Collectively, these data indicate that COX4-1 regulates mitochondrial function in glioma cells independently of BMI1 expression." (PMID 25726526, 2015). "Our results found that miR-340 suppressed BMI1 protein expression in glioma cells, which is consistant with the previous report." (PMID 25831237, 2015). "BMI1 acting as a polycomb group epigenetic gene silencer is highly expressed and correlated with the poor prognosis and progression of glioma patients." (PMID 25831237, 2015). "It was reported that Bmi-1 upregulation protects glioma cells from apoptosis induced by anticancer drugs doxorubicin." (PMID 26429874, 2015). "COX4-1 also promoted the self-renewal of glioma stem-like cells, consistent with the reported role of BMI1 in stem cell growth." (PMID 25726526, 2015). "It was recently reported that BMI1 expression correlates with poor prognosis and glioma progression in patients." (PMID 25726526, 2015). "Immunohistochemical analysis has shown that BMI1 expression in glioma tissues is markedly higher compared with ther normal tissue." (PMID 25999024, 2015). "Here, we examined the role of over-expressed BMI1, a regulator of stem cell self-renewal, in sustaining tumor formation in pediatric glioma stem cells." (PMID 25526772, 2014). "Sean Lawler’s laboratory demonstrated that ectopic expression of miRNA-128 in human glioma neurosphere cultures (having stem-like properties) led to reduction in glioma neurosphere number and volume by down regulating Bmi-1." (PMID 24555688, 2014). "To determine the mRNA expression of BMI1 in pediatric gliomas, we applied qRT-PCR in a panel of 54 pediatric gliomas." (PMID 25526772, 2014). "The present study investigated the response of U87 glioma cells to radiation exposure and the role of Bmi-1 in the response following radiotherapy." (PMID 25364434, 2014). "The current study investigated the response of U87 glioma cells to radiation exposure as well as the role of Bmi-1 in their response following radiotherapy." (PMID 25364434, 2014). "To identify new target genes affected by the silenced BMI1 in CD133+ glioma cells, we performed a series of pair-wise comparisons among the 3 models." (PMID 25526772, 2014). "Bmi-1 has also been reported to be overexpressed in certain gliomas that usually possess a poor prognosis." (PMID 25364434, 2014). "The overall activities of Lenti-BMI1-693 were the strongest, as it is the only lenti-BMI1-shRNA that suppressed cell proliferation in all three glioma models." (PMID 25526772, 2014). "In this study, we confirmed the over-expression of BMI1 in a subset of pediatric gliomas, and showed that the levels of BMI1 mRNA correlated with tumor grade." (PMID 25526772, 2014).
glioma (continued). "In this study, we examined if BMI1 is over-expressed in pediatric gliomas of various pathologic grades and if the over-expression of BMI1 was replicated in our new panel of 8 patient tumor-derived orthotopic xenograft (PDOX) mouse models." (PMID 25526772, 2014). "Bmi1 has been shown to increase angiogenesis, tumor aggressiveness, and resistance to apoptosis in glioma cells by activating the NFκB pathway." (PMID 25348805, 2014). "CM derived from Bmi-1 overexpressing glioma cells stimulated tube-like structures formed by HUVEC cells and HUVEC cell migration." (PMID 23383216, 2013). "We found that the expression of the Bmi-1 in gliomas tumors was significantly larger than embryonal tumors." (PMID 23984324, 2013). "Taken together, these results suggest that Bmi-1 expression modulates the transactivation activity of the VEGF-C promoter harboring the NF-κB binding site in glioma cells." (PMID 23383216, 2013). "Furthermoe, the levels of several NF-κB target genes, TNF-α, IL-6, CCND1, MYC, BcL-XL and MMP-9, were upregulated in Bmi-1-overexpressing, but downregulated in Bmi-1-silenced glioma cells." (PMID 23383216, 2013). "The stimulated HUVEC migration was also reduced by CM derived from Bmi-1-silencing glioma cells when compared with control CM." (PMID 23383216, 2013). "CM derived from Bmi-1-expressing glioma cells induced more tube-like structure formed by HUVEC as well as in shorter time than that by control CM." (PMID 23383216, 2013). "Taken together, the data suggested that Bmi-1 enhanced the capability of glioma cells to stimulate neovascularization in vitro." (PMID 23383216, 2013). "We found that overexpression of Bmi-1 enhanced, whereas knockdown of Bmi-1 diminished, the capability of glioma cells to induce tubule formation and migration of endothelial cells and neovascularization in chicken chorioallantoic membrane." (PMID 23383216, 2013). "Our data provides new insights to the development of novel strategies to inhibit tumor angiogenesis in glioma by targeting Bmi-1, suggesting a necessity of further investigations of the anti-glioma therapeutic value of Bmi-1." (PMID 23383216, 2013). "In the present study, we report that Bmi-1 promotes glioma angiogenesis in vitro as well as in vivo." (PMID 23383216, 2013). "In conclusion, we demonstrate in this study that Bmi-1 induces glioma angiogenesis both in vitro and in vivo, and upregulation of Bmi-1 leads to increased VEGF-C expression through activating NF-κB signaling." (PMID 23383216, 2013). "Collectively, the data suggest that functional NF-κB activation and the consequent VEGF-C expression are essential for the development of the pro-angiogenic phenotype of glioma cells induced by Bmi-1." (PMID 23383216, 2013). "When compared with the controls, gliomas that stably overexpressed Bmi-1 markedly induced vascellum on the surface in the tumor-bearing brain whereas surface vascellum was significantly decreased in brains bearing Bmi-1-knockdown gliomas." (PMID 23383216, 2013). "The major finding of this study is that upregulated Bmi-1 promotes angiogenesis in human gliomas in vitro and in vivo." (PMID 23383216, 2013). "The T test showed a significant difference between the Bmi-1 gene expression, embryonal/gliomas tumor, and high-grade/low-grade tumor (P < 0.05)." (PMID 23984324, 2013). "VEGF-C mRNA was upregulated in Bmi-1-overexpressing glioma cells when compared that in control cells." (PMID 23383216, 2013). "Our previous study has also demonstrated that Bmi-1 is overexpressed, correlates with poor overall survival of patients with gliomas and plays an important role in growth and survival of glioma tumor cells." (PMID 23383216, 2013). "qPCR was used to study the transcription levels of Nestin, Bmi-1 and Sox2 in C6 glioma cells under various concentrations of melatonin." (PMID 24137328, 2013). "Conditioned medium (CM) collectd from Bmi-1-overexpressing glioma cells was added to Matrigels embedded with HUVEC cells." (PMID 23383216, 2013).
glioma (continued). "Subsequently, the effect of Bmi-1 on enhanced ability of glioma cells in inducing in vitro angiogenesis was examined using an in vitro tube-like structure formation assay." (PMID 23383216, 2013). "In vivo, Bmi-1 overexpression and knockdown, respectively, promoted and inhibited angiogenesis in orthotopically transplanted human gliomas." (PMID 23383216, 2013). "A172 and LN229 glioma cells were engineered to overexpress Bmi-1 via stable transfection or to be silenced for Bmi-1 expression using RNA interfering method." (PMID 22967049, 2012). "In conclusion, this study demonstrates that Bmi-1 is upregulated and promotes an aggressive phenotype in glioma via activation of the NF-kappaB signaling pathway, leading to increased MMP-9 expression and activity." (PMID 22967049, 2012). "Western blotting confirmed that Bmi-1 protein expression was silenced in glioma cells transduced with pSuper-retro-puro-Bmi-1-RNAi retroviral vector." (PMID 22967049, 2012). "In the present study, we observed that overexpression of Bmi-1 promoted, whereas knockdown of Bmi-1 inhibited, the invasion and migration of glioma cells." (PMID 22967049, 2012). "Here, we demonstrate that the combination of IL-1β and TGF-β can promote self-renewal and oncogenic capability of glioma cells by inducing expression of stemness factor genes Bmi-1, LIF and Notch-2." (PMID 22330721, 2012). "Taken together, these data suggested that overexpression of Bmi-1 promoted the migration and invasiveness of glioma cells in vitro." (PMID 22967049, 2012). "Wound healing assays demonstrated that ectopic expression of Bmi-1 accelerated the migration of glioma cells." (PMID 22967049, 2012). "Collectively, these results indicated that the overexpression of Bmi-1 induced an aggressive phenotype in glioma cells by activating NF-kappaB signaling, leading to the upregulation of the NF-kappaB target gene MMP-9." (PMID 22967049, 2012). "Correlation studies in glioma specimens showed that Bmi-1 expression significantly correlated with the expression of MMP-9 (P < 0.01)." (PMID 22967049, 2012). "Ectopic overexpression of Bmi-1 dramatically increased, whereas knockdown of endogenous Bmi-1 reduced, the invasiveness and migration of glioma cells." (PMID 22967049, 2012). "Taken together, these results indicated that Bmi-1 promoted the transactivation activity of the NF-kappaB binding site present in the MMP-9 promoter in glioma cells." (PMID 22967049, 2012). "Taken together, our data provide new insights in the development of novel strategies to prevent tumor invasion in glioma by inhibiting the expression of Bmi-1." (PMID 22967049, 2012). "miR-128 and miR-27ab were among these miRs that bind nearest to the start of the 3′UTR, an interesting observation given that miR-128 has been shown to target Bmi1 and E2F3a, thereby promoting an undifferentiated self renewal state in glioma cells." (PMID 21358821, 2011). "Similar to our results, BMI1 had been recently reported preferentially expressed in holoclones derived from glioma cell line." (PMID 21826251, 2011). "In the context of Bmi-1 knockdown, both of these transcription factorsare downregulated in neurons and glioma cells respectively." (PMID 21445297, 2011). "Down-regulated miRs-124 and -137 are involved in the differentiation of glioma stem cells, occurring with miR-128 that targets Bmi1 and E2F3a, promoting a pro-survival, undifferentiated self-renewing state." (PMID 21358821, 2011). "In the presence of EGF stimulus, Bmi-1 localizes in chromatin of glioma stem cells (GSCs), evidenced by the fact that Bmi-1 in GSCs co-localizes with histone H3 in the immunocytochemistry image (data not shown)." (PMID 21305053, 2011). "Additionally, BMI1 enhances the migration and invasion of glioma cells through pathways, such as the NF-κB and MMP-9 pathways." (PMID 41141394, 2026). "These opposing findings highlight the complexities of Bmi‐1's prognostic role in gliomas." (PMID 39791545, 2025).
glioma (continued). "However, malignant glioma cells can resist cytotoxic treatment‐induced cell death upon the upregulation of the oncoprotein Bmi‐1 during glioma progression." (PMID 39791545, 2025). "We hereby aim to explore the specific involvement of Bmi‐1 in glioma pathogenesis." (PMID 39791545, 2025). "Bmi‐1, through the induction of phosphorylation of IKKb and IκBa and co‐localization with the catalytic subunit of NF‐κB in the cell nucleus of tumor cells, activates NF‐κB and renders glioma cells resistant to cytotoxic treatments." (PMID 39791545, 2025). "Both USP22 and Bmi‐1 regulate a series of genes involved in glioma stemness." (PMID 39791545, 2025). "Additionally, Bmi‐1 promotes neovascularization by upregulating VEGF‐C expression in glioma cells upon NF‐kB activation." (PMID 39791545, 2025). "Through regulatory mechanisms, Bmi‐1 may remodel the tumor microenvironment and make it a well‐suitable environment for GSCs to maintain the undifferentiated state of glioma initiating cells (GICs)." (PMID 39791545, 2025). "Indeed, Bmi‐1 overexpression promotes tumor growth and proliferation and is usually correlated with poor prognosis and high‐grade gliomas." (PMID 39791545, 2025). "They analyzed The Glioma French, the Cancer Genome Atlas (TCGA), and the Chinese Glioma Genome Atlas datasets, reporting that the expression of Twist 1 [a gene that stimulates the stemness markers such as BMI1, CRIPTO1, DPPA2, KLF4, and SOX2 in CSC] is related to a poor prognosis in GB patients." (PMID 39153092, 2024). "Serum-induced differentiation of GSCs is associated with loss of tumorigenicity and differentiated glioma cells (DGCs) expressed low levels of the GSC marker SOX2 and BMI1 as well as high levels of astrocytes marker GFAP, which is consistent with previous studies." (PMID 37980347, 2023). "Also, in a study on glioma cells, the upregulation of the Bmi-1 gene promoted cell migration and invasion via the NF-kB-mediated upregulation of MMP-3." (PMID 38137108, 2023). "Similarly, Bmi-1 promotes glioma invasion by activating NF-κB/MMP3 or NF-κB/MMP9 signaling pathways." (PMID 35897796, 2022). "However, cyclopamine does not suppress BMI1 mRNA levels, Gli1 overexpression only marginally increases BMI1 mRNA levels in Daoy glioma spheres." (PMID 33499351, 2021). "Moreover, secretion of BMI1 as well as EZH2 was observed as an independent prognostic factor for overall survival in glioma patients." (PMID 34745848, 2021). "BMI1 inhibitors impair tumor growth and suppress glioma and lung cancer tumorigenesis." (PMID 33499351, 2021). "Mesenchymal glioma stem cells are sensitive to a BMI1 inhibitor." (PMID 33499351, 2021). "Furthermore, DANCR acted as a ceRNA to regulate BMI1 expression and BMI1-mediated effects on progression of glioma by sponging miR-135a-5p." (PMID 32099526, 2020). "Interestingly, an online software Tarbase v8.0 was carried out, and the results showed that there are potential binding sites of BMI1 in miR-135a-5p, thus we needed to probe their relationship in glioma." (PMID 32099526, 2020). "Bmi-1 is reported to active NF-κB signaling in glioma angiogenesis, cell migration and invasion." (PMID 32125276, 2020). "Importantly, Bmi1 is known to regulate miRNAs, such as miR10a that has been shown to repress EphA8 in glioma cells, mediating the epithelial–mesenchymal transition and promoting cell migration and invasion." (PMID 31988455, 2020). "Moreover, DANCR acted as a ceRNA to regulate BMI1 expression and BMI1-mediated effects on progression of glioma by sponging miR-135a-5p." (PMID 32099526, 2020). "In addition, the expression level of BMI1 was markedly upregulated in glioma tissues in contrast to normal tissues, and the level of BMI1 protein was significantly elevated in LN229 and U251 cells relative to NHAs cells." (PMID 32099526, 2020).